INS (insulin)
Diseases named in the same sentence as INS in open-access papers (continued):
Sharing a sentence is not in itself a finding about the gene and the disease.
Alzheimer disease (continued). "In addition, the insulin signaling transduction pathway can inhibit Aβ production and the hyperphosphorylation of microtubule-related protein tau through multiple pathways, so impaired insulin signaling can accelerate the progression of Alzheimer’s disease (AD)." (PMID 37415663, 2023). "In the bar graphs, within the top (most significant by p value) 10 pathways for European Americans, we observed pathways for insulin/IGF, mannose metabolism, Alzheimer’s disease, and T-cell activation." (PMID 37220136, 2023). "Melatonin, insulin, and Δ9-tetrahydrocannabinol (THC) have been shown to reverse cognitive deficits and attenuate neuropathologies in transgenic mouse models of Alzheimer’s disease (AD) when used individually." (PMID 36830601, 2023). "Insulin reduced amyloidogenesis and COX-2-mediated neuroinflammation in astrocytes treated with streptozotocin, which are hallmarks of Alzheimer’s disease." (PMID 36233271, 2022). "Moreover, type 3 diabetes has recently been described, in which it is proposed that neural resistance to insulin would be at the origin of Alzheimer’s disease, so ranolazine could also be a drug to be considered in the preventive treatment of Alzheimer’s disease." (PMID 36233271, 2022). "Increased insulin level in the brain contributes to Alzheimer’s Disease pathology, as the insulin-degrading enzyme (IDE) also takes part in degrading senile plaques, and in insulin resistance, it is involved in degrading insulin." (PMID 34885795, 2021). "Different genes express identified Pathways such as Notch signaling pathways relating to Alzheimer’s disease, peroxisome proliferator-activated receptor (PPAR), adipocytokine, insulin, PI3K–Akt, mTOR, and AMPK signaling pathways." (PMID 34306005, 2021). "A fourth study assessed summary statistics from the Meta-Analyses of Glucose and Insulin-related traits Consortium and the IGAP Alzheimer’s disease summary statistics." (PMID 33868373, 2021). "These events may lead to an increase in insulin resistance, peripheral vascular resistance resulting in the development of hypertension, metabolic syndrome and coronary heart disease and CNS disorders such as Alzheimer’s disease, and other chronic inflammatory diseases seen with increasing age." (PMID 33567774, 2021). "The pathogenesis of Alzheimer’s disease is complex and involves multiple genetic and environmental factors, and our purpose is to present a new hypothesis that links mitochondrial dysfunction, cerebral energetics, cerebral insulin resistance, and diet that might encourage further research." (PMID 33024433, 2020). "KEGG pathway analysis for these genes identified several key signaling pathways, including the insulin signaling pathway, Parkinson's disease, non-alcoholic fatty liver disease (NAFLD), glucagon signaling pathway, and Alzheimer's disease." (PMID 32194838, 2020). "This review will explore the literature to date on the role of insulin in neurotrauma and neurodegeneration, with a focus on traumatic brain injury (TBI), spinal cord injury (SCI), Alzheimer’s disease (AD) and Parkinson’s disease (PD)." (PMID 33100956, 2020). "A reduced insulin/IGF-1 signaling in experimental animal model protects the mammalian brain from amyloid-β toxic effects, neurodegeneration, and Alzheimer disease." (PMID 29149058, 2017). "Disturbances in insulin and possibly insulin growth factor-1 (IGF-1) signaling in the brain, especially the hippocampus, have been observed in Alzheimer’s disease." (PMID 25755673, 2015). "The insulin/IGF1 signalling (IIS) pathways are involved in longevity regulation and are dysregulated in neurons in Alzheimer’s disease (AD)." (PMID 26297026, 2015). "Serum levels of insulin, IGFs and IGF binding proteins (IGFBPs) are altered in human neurodegenerative diseases of various aetiologies, such as Alzheimer’s disease, amyotrophic lateral sclerosis, and cerebellar ataxia." (PMID 26331037, 2014).
Alzheimer disease (continued). "Accumulating evidence suggests that low levels of circulating IGF-1 and impairments of insulin/IGF-1 signaling in the brain contributed to age-dependent cognitive decline, such as Alzheimer’s disease." (PMID 25247581, 2014). "Although IDE catalyzes degradation of insulin and β-amyloid peptide, current knowledge about IDE regulation is mostly derived from the study of β-amyloid peptide in the Alzheimer disease field." (PMID 24740421, 2014). "Finally, insulin signaling, in particular the down-regulation of the insulin receptor substrate 4 (Irs4) gene, may be an important event in the transition from age-related changes to Alzheimer’s disease specific-changes." (PMID 24274089, 2013). "This study is aimed at establishing the effects of lipoic acid, on glucose uptake, insulin signaling through the PI3K/Akt pathway, and synaptic plasticity on a triple transgenic mouse model of Alzheimer’s disease (3xTg-AD)." (PMID 23875003, 2013). "Subsequently, post-mortem brain studies unveiled that cerebral insulin, insulin receptor and IGF levels are inversely proportional with the progression of Alzheimer's disease." (PMID 22369239, 2012). "In addition, as recent studies have shown that insulin and leptin resistance in extra-hypothalamic brain regions may relate to neurological disorders, such as Alzheimer's disease and depression, it will be exiting to evaluate the participation of TLRs and high-fat feeding in these contexts." (PMID 19340313, 2009). "Based on the current paper focusing on mechanisms associated with late-onset Alzheimer’s disease (LOAD)—i.e., mitochondrial dysfunction, insulin resistance, oxidative injury—these factors were not known to only characterize LOAD." (PMID 41003796, 2025). "Intranasal treatment of the intracerebroventricular-streptozotocin (ICV-STZ)-induced mouse model of Alzheimer’s disease with the insulin sensitizer metformin improved learning and memory without altering the blood levels of glucose." (PMID 40006083, 2025). "The non-traumatic intranasal way of insulin delivery was successfully applied in clinical trials to treat patients with Alzheimer’s disease, Parkinson’s disease and other neurodegenerative disorders." (PMID 39057034, 2024). "Preclinical and clinical evidence suggested that intranasal insulin improves memory function and can also improve functional performance in patients with Alzheimer’s disease (AD) and Parkinson’s disease (PD)." (PMID 38915348, 2024). "Overall, the preliminary autoradiography studies in both rodent and non-human primate models of Alzheimer's disease points to lower uptake of [68Ga]-NOTA-insulin in Alzheimer's disease brains compared to controls." (PMID 39267777, 2024). "Furthermore, the potent antioxidant melatonin has the ability to improve insulin secretion, normalize glucose levels, reduce IR, and slow the progression of cognitive dysfunction in patients with T2DM and Alzheimer’s disease (AD)." (PMID 39000130, 2024). "IR within the peripheral tissues has been hypothesized by some to alter neuronal insulin signaling and contribute to the development of neurofibrillary tangles (NFT), one of the pathologic hallmarks of Alzheimer’s disease (AD)." (PMID 36932429, 2023). "Fasting insulin PRS 3 was also significantly negatively associated with all-cause dementia (HR = 0.94; uncorrected P-value = 4.3e-02) and PRS 7 with Alzheimer’s disease (HR = 0.86; uncorrected P-value = 1.6e-02), although not after Bonferroni correction." (PMID 37091584, 2023). "One major example is represented by the IN drug delivery of insulin, investigated in the SNIFF clinical trials as a possible treatment for cognitive defects in patients affected by Alzheimer’s disease (clinicaltrials.gov: NCT03857321, NCT00438568, NCT01767909)." (PMID 36834804, 2023). "Several studies have shown that patients with Alzheimer’s disease (AD) have desensitized insulin signals in their brains, even in the absence of DM." (PMID 36776436, 2023).
Alzheimer disease (continued). "The result of this phase II study showed promising treatment outcomes, as the administration of intranasal insulin improved delayed memory ability, Dementia Severity Rating Scale (DSRS) score, and Alzheimer Disease’s Assessment Scale—cognitive subscale (ADAS-cog) score." (PMID 37511207, 2023). "Insulin promotes the secretion of BDNF, which promotes neurite length, synaptic formation, and neuronal cell survival, and ultimately improves depressive mood disorder and Alzheimer’s disease pathologies." (PMID 35328405, 2022). "Intranasal insulin was found to improve cognitive functions in patients with Alzheimer’s disease with no increase in peripheral blood levels." (PMID 35885011, 2022). "Moreover, in the brain, insulin plays a key role in the direct regulation of ERK, which is involved in maintaining the type of memory involved in Alzheimer’s disease." (PMID 36233271, 2022). "KEGG pathway analysis indicated that the differentially expressed genes were involved in 107 pathways, including “systemic lupus erythematosus”, “lipid metabolism”, “Alzheimer's disease”, “receptor interaction”, “apoptosis”, “MAPK signaling pathway”, and “insulin signaling pathway”." (PMID 35582424, 2022). "As shown here, the role of insulin in the mammalian brain is mainly examined in Alzheimer’s disease and depression, but not in CTA." (PMID 33256267, 2020). "The focus of this review is therefore to characterize the current literature on the role of insulin in CNS disorders, with a focus on traumatic brain injury (TBI), spinal cord injury (SCI), and neurodegenerative diseases, specifically Alzheimer’s disease (AD) and Parkinson’s disease (PD)." (PMID 33100956, 2020). "Impaired downstream signaling of insulin may result in overactivation of GSK-3, and thus can participate in Alzheimer’s disease pathology and the development of dementia." (PMID 31858268, 2020). "This delivery route has been successfully used to rapidly deliver and target insulin to the brain to improve memory in normal healthy adults and in patients with Alzheimer’s disease without altering the blood levels of insulin or glucose." (PMID 32687511, 2020). "However, in a different mouse model of Alzheimer’s disease (APP/PS1), insulin BBB transport rate is significantly increased in specific brain regions including the hippocampus compared to a wild-type mouse." (PMID 31213970, 2019). "Clinical trials have shown the successful use of intranasal insulin to safely improve memory and cognition in patients with mild cognitive impairment or Alzheimer’s disease without alteration in the blood levels of insulin or glucose." (PMID 30386923, 2019). "In addition, our data revealed the effects of RBP4 of DEGs that are important to pathways in GCs, including oxidative phosphorylation, NAFLD, Alzheimer’s disease, fatty acid biosynthesis, AMPK signaling pathway, and insulin signaling pathway." (PMID 31412686, 2019). "Evidence from human studies suggests that intranasal administration of insulin may increase cognitive ability in healthy volunteers and patients with T2DM and Alzheimer’s disease (AD)." (PMID 30909971, 2019). "These analogs may be particularly important because insulin signaling appears to impair the proteostatic response in model systems of several misfolded protein diseases, including ATD and Alzheimer’s disease." (PMID 30673724, 2019). "It should be noted that in this previous study, the T2D patients with Alzheimer’s disease and with mild cognitive Impairment were not obese but were insulin resistant." (PMID 31835729, 2019). "Importantly, we found many pathways involved in obesity-related diseases, such as Alzheimer’s disease, Parkinson’s disease and NAFLD, and in fat deposition in muscle, such as the insulin signaling pathway." (PMID 30843090, 2019).
Alzheimer disease (continued). "The insulin doses administered to humans intranasally in order to improve their cognitive functions are usually 20 or 40 IU, 40 IU was shown to have more pronounced positive effect on people with MCI or Alzheimer’s disease, see, for example." (PMID 31362343, 2019). "Besides, the therapeutic potential of IGF-1 in diseases characterized by impaired hippocampal function needs to be better investigated, especially considering evidence pointing to brain insulin and IGF-1 resistance in Alzheimer's disease patients." (PMID 25977822, 2015). "Decreased insulin and IGF-1 have been observed in Alzheimer's disease brain." (PMID 24860814, 2014). "Furthermore, insulin and IGF-1-induced signaling is reduced in the brains of patients suffering from Alzheimer's disease (AD)." (PMID 22654904, 2012). "Using a Wistar-rat model to mimic Late-Onset Alzheimer’s Disease (LOAD), this study replicated key AD features, including altered liver enzyme levels, muscle weakness, and elevated brain and liver glucose levels, aligning with the observed insulin resistance in AD." (PMID 37891760, 2023). "Therefore, investigating the impact of long-term rapamycin treatment on insulin BBB transport, especially in mouse models of Alzheimer’s disease, still warrants further investigation as a mechanism for contributing to the cognitive improvements due to rapamycin." (PMID 34449653, 2021). "Finally, infusing insulin, without increasing glucose, has been shown to increase memory for Alzheimer’s disease patients." (PMID 32127481, 2020). "Interestingly, insulin administered by intranasal improved cognitive dysfunction and insulin signaling, reduced amyloid-β (Aβ) production and amyloid plaque burden, and increased neurogenesis in 4-month-old APP/PS1 mice showing early Alzheimer's disease (AD) pathologies." (PMID 29850612, 2018). "The reduced insulin fibril formation, structural inertia to glycation involved conformational changes, anti-lipid peroxidation effect, and increasing microglia viability indicated the protective effect of BHB that disclose insight on the possible preventive effect of BHB on Alzheimer’s disease." (PMID 26311627, 2015). "Five treatment conditions of intranasal insulin, that is, 10, 20, 40, or 60 IU, have been applied to 33 memory-impaired adults suffering from Alzheimer's disease or amnestic mild cognitive impairment and 59 adults without Alzheimer's disease that were normal adults." (PMID 26556194, 2014). "Furthermore, disruption of the insulin signaling inhibits the PI3K/Akt pathway, and over-phosphorylation of tau results in the accumulation of neurofibrillary tangles (NFTs) that induce neuron and brain neuronal cell apoptosis, which lead to neurodegenerative diseases like Alzheimer’s disease." (PMID 32575897, 2020). "Also, the activation of PI3K by insulin and IGF-1 is markedly disturbed in Alzheimer Disease (AD) brain, leading to sustained activation of Akt, which in turns causes neurons to become increasingly and ultimately totally resistant to both agonists." (PMID 29358916, 2017). "In the late 1970s, the central nervous system (CNS) was not considered to be an insulin-dependent tissue, but it is now well known that insulin plays a major physiologic role in this tissue and its disturbances, being involved in certain neurodegenerative states, such as Alzheimer’s disease (AD)." (PMID 25346723, 2014). "In case of Alzheimer’s disease GSK-3α is involved in the regulation of amyloid processing and insulin was demonstrated facilitating its non-amyloidogenic pathway." (PMID 31858268, 2020).
Alzheimer disease (continued). "However, KO animals showed a higher expression in the insulin-IGF pathways in the Hippocampus, a brain area related to the pathogenesis of Alzheimer’s disease, and this was true irrespective of diet, suggesting for these molecules a protective role toward functional alterations induced by HFD." (PMID 38344021, 2024).
steatosis (706 papers, 2006 to 2026). Increased lipid within the cytoplasm of cells. "Delayed changes, such as focal steatosis and glycogen accumulation appear days to weeks after Tx and are caused by local overstimulation of hepatocytes by insulin in supraphysiological concentrations." (PMID 41683841, 2026). "The resulting excess of free fatty acids inhibits liver insulin sensitivity and facilitates lipogenesis, causing steatosis and cirrhosis." (PMID 41190151, 2025). "Long-term weight loss also has the potential to reverse steatosis and improve insulin sensitivity, reduce inflammation as well." (PMID 39860434, 2025). "Association between 24h insulin dosage and severity of steatosis or fibrosis: Among all participants, we observed a positive correlation between daily insulin dosing with both steatosis and fibrosis scores." (PMID 40568565, 2025). "As such, we were interested in evaluating the therapeutic efficacy of targeting ASPG to ameliorate steatosis-associated systemic insulin signal defects." (PMID 40760121, 2025). "Improved insulin sensitivity plays a key role in the management of NAFLD as the dysfunction of the insulin pathway causes the flow of FAs to the liver, increases TG synthesis and storage, inflammation, steatosis, and oxidative stress in the body." (PMID 40913543, 2025). "At the hepatic level, the observed profile (reduced lipogenesis, increased fatty acid oxidation, and decreased steatosis) is associated with improved insulin sensitivity and reduced lipotoxic stress." (PMID 40650183, 2025). "It seems that M2 macrophages were associated with improved insulin sensitivity and reduced steatosis in MAFLD." (PMID 39851524, 2025). "Dysfunctional insulin-resistant adipose tissue underlies the development of advanced fibrosis in T2DM beyond the BMI or steatosis." (PMID 39131144, 2024). "Whole-body knockout (KO) of ATGL improved insulin sensitivity but also caused severe steatosis in the heart and liver, as well as cardiac dysfunction." (PMID 37432201, 2023). "In parallel, we found that the onset of the primary pathogenic features of NAFLD, namely steatosis, hepatic insulin resistance, inflammation and fibrosis, occurred earlier in liver-specific PARKIN knockout mice in response to WD feeding." (PMID 37165006, 2023). "Hepatic ceramide and diacylglycerol (DAG) accumulation are each considered potential culprits in insulin resistance related to steatosis, and steatosis-related inflammation also appears to be linked to insulin sensitivity." (PMID 37432201, 2023). "Steatosis grade was also associated with impaired fasting glucose, HbA1c, insulin, and fasting plasma glucose levels." (PMID 35797133, 2022). "Inhibition and siRNA or genetically mediated knockdown of the enzyme has demonstrated considerable metabolic benefits to weight loss, insulin sensitivity, and steatosis in mice." (PMID 36356832, 2022). "On the contrary, mice with knock-out for glcm coding for the modifier subunit of GCL are protected against the development of HFD- or methionine-choline deficient diet (MCD)-induced steatosis, inflammation and fibrosis, and they maintain insulin sensitivity." (PMID 35740032, 2022). "Gene set enrichment analysis on the KEGG database for the patients with steatosis revealed pathways associated with cell cycle regulation, regeneration, apoptosis, and insulin signaling." (PMID 34568346, 2021). "In case of miR-486-5p, insulin signaling and resistance are linked to hepatic glucose output and increased steatosis." (PMID 36303988, 2021). "This high amount of FFA in liver cells can cause intracellular inflammation, insulin resistance, and hepatocyte steatosis elevation in the liver." (PMID 33793621, 2021). "Relatively moderate weight loss (as low as 10% of body weight) has been shown to improve insulin resistance and reduce steatosis, while massive weight loss following bariatric surgery can ameliorate NASH with the reversal of cirrhosis." (PMID 32443737, 2020).